TNFSF11 (TNF superfamily member 11)
Description:
Cytokine that binds to TNFRSF11B/OPG and to TNFRSF11A/RANK. Osteoclast differentiation and activation factor. Augments the ability of dendritic cells to stimulate naive T-cell proliferation. May be an important regulator of interactions between T-cells and dendritic cells and may play a role in the regulation of the T-cell-dependent immune response. May also play an important role in enhanced bone-resorption in humoral hypercalcemia of malignancy. Induces osteoclastogenesis by activating multiple signaling pathways in osteoclast precursor cells, chief among which is induction of long lasting oscillations in the intracellular concentration of Ca (2+) resulting in the activation of NFATC1, which translocates to the nucleus and induces osteoclast-specific gene transcription to allow differentiation of osteoclasts. During osteoclast differentiation, in a TMEM64 and ATP2A2-dependent manner induces activation of CREB1 and mitochondrial ROS generation necessary for proper osteoclast generation (By similarity).
Synonyms: ODF; OPGL; RANKL; TRANCE; CD254; OPTB2; TNLG6B; hRANKL2; sOdf
Tractability: Small molecule: a high-quality ligand is known. Antibody: an approved drug acts on it; its Gene Ontology location is reachable by antibodies, with high confidence; UniProt places it where antibodies can reach, with medium confidence; UniProt predicts a signal peptide or a membrane-spanning region. PROTAC: a small molecule that binds it is known.
Target class: Secreted protein
Gene: Protein-coding gene on chromosome 13 (42,562,736 to 42,608,013, forward strand). Ensembl gene ENSG00000120659.
Subcellular location: Cell membrane (Isoform 1); Cell membrane (Isoform 3); Cytoplasm (Isoform 2); Secreted (Tumor necrosis factor ligand superfamily member 11, soluble form)
Pathways (Reactome):
Immune System: TNF receptor superfamily (TNFSF) members mediating non-canonical NF-kB pathway; TNFR2 non-canonical NF-kB pathway; TNFs bind their physiological receptors
Developmental Biology: Transcriptional and post-translational regulation of MITF-M expression and activity
Gene Ontology:
Molecular function: cytokine activity; protein binding; tumor necrosis factor receptor binding; identical protein binding; receptor ligand activity; tumor necrosis factor receptor superfamily binding
Biological process: cytokine-mediated signaling pathway; monocyte chemotaxis; osteoclast differentiation; positive regulation of bone resorption; positive regulation of ERK1 and ERK2 cascade; positive regulation of homotypic cell-cell adhesion; positive regulation of intracellular signal transduction; positive regulation of MAPK cascade; positive regulation of non-canonical NF-kappaB signal transduction; positive regulation of osteoclast differentiation; positive regulation of T cell activation; positive regulation of transcription by RNA polymerase II; tumor necrosis factor-mediated signaling pathway; calcium-mediated signaling; cell surface receptor signaling pathway; immune response; positive regulation of canonical NF-kappaB signal transduction; positive regulation of corticotropin-releasing hormone secretion; positive regulation of extrinsic apoptotic signaling pathway; positive regulation of fever generation by positive regulation of prostaglandin secretion; cell communication; negative regulation of transcription by RNA polymerase II; signaling
Cellular component: extracellular region; plasma membrane; cytoplasm; membrane
Genetic constraint (gnomAD): Loss-of-function variants: 12 observed, 32.23 expected, observed/expected ratio (o/e) 0.37, 90% interval 0.24 to 0.6. The upper end of that interval is the gene's LOEUF score, 0.6, which puts it in group 2 of 6, group 1 being the genes least tolerant of losing a copy. Missense variants: 345 observed, 391.57 expected, observed/expected ratio (o/e) 0.88, 90% interval 0.81 to 0.96. Synonymous variants: 172 observed, 145.35 expected, observed/expected ratio (o/e) 1.18, 90% interval 1.04 to 1.34.
Gene-disease validity (ClinGen):
ClinGen rates the evidence that TNFSF11 causes each of these diseases.
autosomal recessive osteopetrosis 2 (autosomal recessive): Definitive.
Homologues: Orthologues: chimpanzee TNFSF11 (99% identical), macaque TNFSF11 (98% identical), rabbit TNFSF11 (92% identical), pig TNFSF11 (91% identical), guinea pig TNFSF11 (89% identical), dog TNFSF11 (87% identical), mouse Tnfsf11 (83% identical), rat Tnfsf11 (81% identical), tropical clawed frog tnfsf11 (39% identical), zebrafish tnfsf11 (20% identical). Paralogues in human: TNFSF10 (23% identical), CD40LG (15% identical), LTB (14% identical), FASLG (14% identical), TNFSF14 (14% identical), TNFSF15 (13% identical), LTA (12% identical), TNF (11% identical).
Diseases named in the same sentence as TNFSF11 in open-access papers:
TNFSF11 is named in the same sentence as 495 diseases in open-access papers, as found by Europe PMC text mining. Sharing a sentence is not in itself a finding about the gene and the disease. The quoted sentences say what the papers report.
osteoporosis (1,002 papers, 2007 to 2026). A condition of reduced bone mass, with decreased cortical thickness and a decrease in the number and size of the trabeculae of cancellous bone (but normal chemical composition), resulting in increased fracture incidence. "These genes were selected as variables to construct a molecular risk model for predicting osteoporosis (risk score = Exp (CTNNB1) × (−1.167227) + Exp (MITF) × (−5.192496) + Exp (TNFSF11) × (12.019122))." (PMID 37893075, 2023). "Based on the osteoclast-regulatory genes (CTNNB1, MITF, and TNFSF11) in the risk model, we used the R package “ConsensusClusterPlus” to cluster the osteoporosis patients." (PMID 37893075, 2023). "CTNNB1 and MITF are protective factors, whereas TNFSF11 is a risk factor for osteoporosis." (PMID 37893075, 2023). "For example, a cis-pQTL for TNFSF11 (RANKL) overlapped with GWAS signals for osteoporosis and hypothyroidism." (PMID 37563310, 2023). "In this study, we detected three key genes, CTNNB1, MITF, and TNFSF11, using microarray data for osteoporosis." (PMID 37893075, 2023). "In conclusion, CTNNB1, MITF, and TNFSF11 were identified as three key genes involved in the occurrence and development of osteoporosis." (PMID 37893075, 2023). "Because of the crucial role of OPG and RANKL in bone remodeling, the genes encoding for OPG (TNFRSF11B; gene map locus 8q24.12) and RANKL (TNFSF11; gene map locus 13q14) have been considered as promising candidates for osteoporosis." (PMID 33572979, 2021). "Different studies have been able to identify single nucleotide polymorphisms (SNPs) in TNFSF11 (RANKL) and TNFRSF11B (OPG) genes in association with osteoporosis or low bone density." (PMID 26065000, 2015). "Examples of genetically anchored protein–disease connections included: TNFSF11 (RANKL) with osteoporosis and hypothyroidism, NGF (nerve growth factor) with migraine, TNFSF12 (TWEAK) with hypertension and fibroblast growth factor 5 (FGF5) with hypertension and cardiovascular diseases." (PMID 37563310, 2023). "In addition, DNA methylation was found to repress TNFSF11 transcription which induces osteoclastogenesis in vitro, and affects the transcription expression of RANKL-OPG ratio indicating pathogenesis of primary osteoporosis." (PMID 35510247, 2022). "Taken together, these data support the concept that loss of Lrp1 in osteoblasts leads to increased osteoblast PDGF signaling, which in turn stimulates Tnfsf11 expression and thereby increases osteoclast numbers and activity, resulting in severe osteoporosis of all bone compartments in mice." (PMID 29507818, 2018). "The key roles of these three genes in osteoporosis were verified using multivariate logistic regression, with CTNNB1 (OR = 3.501 × 10−7, p = 0.016) and MITF (OR = 2.475 × 10−14, p = 0.002) as protective factors and TNFSF11 (OR = 9.245 × 1022, p = 0.003) as a risk factor." (PMID 37893075, 2023). "In one GWAS, key genes involved in osteoporosis were TNFRSF11B (OPG), TNFSF11 (RANKL), LRP5, and ESR1." (PMID 40772209, 2025). "The dysregulation of TNFSF11/RANKL disturbs the delicate equilibrium between bone resorption and formation, contributing to the pathogenesis of osteoporosis." (PMID 37875547, 2023). "TNFSF11 was significantly upregulated (p = 0.001), whereas CTNNB1 (p = 0.001) and MITF (p = 0.017) were significantly downregulated, in the osteoporosis group." (PMID 37893075, 2023). "Denosumab can target RANKL, which is known as TNFSF11 in the TNF superfamily, and treat osteoporosis, which fully illustrates the link between AS and LBMD." (PMID 36468006, 2022). "In the past two decades, it has been well demonstrated that RANKL (also known as TNFSF11) binding to its receptor RANK (also known as TNFRSF11A) drives osteoclast development and it is considered a crucial target protein for osteoporosis treatments." (PMID 33406741, 2021).
osteoporosis (continued). "While genetic associations and epigenetic alterations in the TNFSF11 gene (RANKL) have been well-linked to metabolic bone diseases of the skeleton, particularly osteoporosis, they have never been addressed in OTSC." (PMID 35510247, 2022). "Furthermore, CTSK, CSF1, TNFSF11, CTNNB1, TNFRSF11A, and TNF may be the most promising osteoporosis markers." (PMID 37893075, 2023). "Several mechanisms are known to contribute to the pathology of menopause-induced primary osteoporosis such as increased expression of tumour necrosis factor (TNF) superfamily members TNFα (TNFSF2) and receptor activator of nuclear factor kappa-B ligand (RANKL; TNFSF11)." (PMID 31299941, 2019).
periodontitis (381 papers, 2012 to 2026). An acute or chronic inflammatory process that affects the tissues that surround and support the teeth. "However, our results suggest that osteoclastogenesis in periodontitis is mainly dependent on RANKL and IL-6, as the expression of Tnfsf11 and Il6 was markedly increased, whereas the change in Tnf expression was mild." (PMID 38548743, 2024). "Thus, the aim of this study was to evaluate the influence of the TLR4 A896G (rs4986790), TLR4 C1196T (rs4986791), CD14 C-260T (rs2569190), RANKL (TNFSF11, rs2277438), and OPG (TNFSF11B C163T, rs3102735) polymorphisms in periodontitis." (PMID 31281226, 2019). "Interestingly, exFoxp3TH17 cells in periodontitis-induced mice had much higher expression levels of effecter molecules such as Rorc, Il17a, Il17f, and Tnfsf11 than conventional TH17 cells." (PMID 29453398, 2018). "Previous studies have shown that activated T and B cells in gingival tissues of individuals with periodontitis express RANKL (receptor activator of nuclear factor κB ligand, also known as TNFSF11)." (PMID 34594237, 2021). "Thus, the aim of this study was to evaluate the influence of the polymorphisms in TLR4 (rs4986790 and rs4986791), CD14 (rs2569190), RANKL (TNFSF11, rs2277438), and OPG (TNFSF11B, rs3102735) in the development of periodontitis." (PMID 31281226, 2019).
breast cancer (367 papers, 2003 to 2026). A primary or metastatic malignant neoplasm involving the breast. "Recently, several studies have reported that TNFSF11 (namely RANKL) is closely related to breast cancer, gastric cancer, cervical, endometrial, prostate cancer, and cancer-related bone metastasis." (PMID 38594779, 2024). "For example, evidence from preclinical studies has suggested RANKL (TNFSF11) as a target with strong potential to prevent breast cancer bone metastasis." (PMID 34064392, 2021). "The authors reported that receptor activator of nuclear factor κB ligand (RANKL; TNFSF11) enhanced breast cancer metastasis to the TE bone and formation of osteolytic lesions." (PMID 29685995, 2018). "The unexpected link between diaphysis BMFF genes and mammary gland development, which involves common associations with ESR1, TNFSF11, and TNFSFR11A, may also relate to such putative BMAT-breast cancer relationships." (PMID 39747859, 2025). "Similarly, the level of Tnfsf11 and Tnfrsf11a encoding respectively for the secreted factor RANKL and its receptor, RANK, involved in the oncogenesis of Brca1 mutation-driven breast cancer, was not altered in the absence of Itgα6." (PMID 38835038, 2024).
rheumatoid arthritis (220 papers, 2006 to 2025). A chronic, systemic autoimmune disorder characterized by inflammation in the synovial membranes and articular surfaces. "Increased mRNA expression of Tnfsf11 and soluble RANKL protein has also been observed in synovial fibroblasts from patients with rheumatoid arthritis." (PMID 31379855, 2019).
Arthritis (175 papers, 2005 to 2026). Inflammation of a joint. "Notably, some dermal DEGs (Tnfsf11, Ctsk, Mmp3, Mmp8, etc.)were associated with osteoclast differentiation and activation, which is linked to arthritis." (PMID 40471688, 2025). "In the animal model of arthritis induced by collagen or adjuvant, the level of serum TNFSF11 was significantly increased." (PMID 31988808, 2020).
myeloma (151 papers, 2007 to 2025). "Our study elucidates a molecular mechanism for the osteocyte-myeloma interaction, in which myeloma cell TP/2DDR upregulates CIITA expression in osteocytes; the increased CIITA enhances histone acetylation of TNFSF11 and SOST genes; and promotes RANKL and sclerostin secretion from osteocytes." (PMID 35760800, 2022).
prostate carcinoma (119 papers, 2003 to 2025). A carcinoma that arises from epithelial cells of the prostate gland. "As Runx2 has been implicated in RANKL expression in various cell types, such as prostate cancer cells, vascular smooth muscle cells, and osteoblasts, we further examined whether CrkL-inhibited Tnfsf11 expression is involved in the regulation of Runx2 expression." (PMID 34209812, 2021). "Recent research has revealed that the expression level of NOTCH1, BAP1, and TNFSF11 is closely related to bone metastasis in prostate cancer." (PMID 38384328, 2024).
osteopetrosis (111 papers, 2008 to 2026). Osteopetrosis, also known as marble bone disease, is a descriptive term that refers to a group of rare, heritable disorders of the skeleton characterized by increased bone density on radiographs. "AR RANKL deficiency has been reported in nine patients from seven unrelated kindreds suffering from osteopetrosis caused by homozygosity for variants of the TNFSF11 gene predicted to be deleterious." (PMID 41608125, 2025). "For example, individuals with osteopetrosis carrying mutations in TNFSF11 (encoding RANKL) were prone to bone fractures and their bone biopsy specimens lacked osteoclasts." (PMID 37714410, 2023). "IKBKG, LRP5, and TNFSF11 are mainly due to the interaction of osteoblasts and osteoclasts, which cause an imbalance between bone formation and bone absorption, resulting in osteopetrosis." (PMID 37373559, 2023). "Moreover, TNFSF11 has already been linked to a series of diseases with osteoproliferation or osteolysis, including osteopetrosis, dysosteosclerosis, Paget disease of bone 2, and familial expansile osteolysis." (PMID 37008941, 2023). "A Tnfsf11-deficient mouse exhibits the typical osteopetrosis changes, which may provide the experimental data and theoretical foundation for the study of craniofacial and dental phenotypes." (PMID 37373559, 2023). "RANKL or TNFSF11 was a causative gene for osteoclast‐poor osteopetrosis." (PMID 34056870, 2021). "Osteopetrosis in TNFSF11-deficient patients requires a different treatment approach." (PMID 33162933, 2020). "However, osteopetrosis caused by TNFSF11 mutations cannot be treated by HSCT, because an osteoblast defect is the basis of this pathology." (PMID 25873953, 2015). "In our previous study, we found that Tnfsf11 CKOAdipoq mice develop osteopetrosis at 1 month of age while Tnfsf11 CKODmp1 mice at the same age have normal bone mass." (PMID 36779854, 2023). "A link between TNFSF11 and autosomal recessive osteoclast‐poor osteopetrosis was established in 2007." (PMID 34056870, 2021). "Osteopetroses with developmental defects of osteoclasts (osteoclast-poor osteopetrosis) are more rare, secondary to diseases caused by mutations in TNFRSF11A or TNFSF11, encoding RANK and RANKL, respectively." (PMID 33081155, 2020). "Several pre-clinical studies have shown promising results in the treatment of TNFSF11-dependent osteopetrosis." (PMID 33162933, 2020). "Less than 4% of ARO patients harbors loss-of-function mutations of TNFSF11, encoding RANK-L, or of TNFRSF11A, encoding RANK receptor, and constitute a distinct subgroup of recessive osteopetrosis." (PMID 25873953, 2015). "TNFSF11 mutants suffer severe osteopetrosis, tooth anomalies, and mammary gland defects." (PMID 39857285, 2025). "When osteopetrosis is diagnosed in early life (i.e., before 3 years of age), HSCT can cure ARO and IARO, except when associated with mutations in some genes such as TNFSF11, which encodes osteoclast differentiation factor (ODF or RANKL)." (PMID 38017429, 2023). "HSCT treatment for TNFSF11 mutations will be ineffective because in this form of osteopetrosis the main defect does not arise from the haematopoietic lineage." (PMID 33162933, 2020). "As is known, most osteopetrosis forms can be treated with Haematopoietic Stem Cell Transplantation (HSCT); despite this, in the presence of neurodegenerative forms, as well as when osteopetrosis is caused by mutations in the TNFSF11 gene, the treatment is contraindicated." (PMID 36360203, 2022). "Deletion of the genes coding for either RANK or RANKL (Tnfrsf11a and Tnfsf11, respectively), blocks OCL production and leads to severe osteopetrosis in mice and in humans, indicating that RANK-RANKL signaling is critical for osteoclastogenesis." (PMID 33912557, 2021).
diabetes (95 papers, 2009 to 2025). "However, our study found that the mutation rate of rs9533156 in the TNFSF11 gene of diabetic gastric cancer patients is higher, suggesting that diabetes may be related to gastric cancer, and diabetic patients have a higher risk of gastric cancer." (PMID 32655638, 2020).
osteosarcoma (71 papers, 2007 to 2025). A usually aggressive malignant bone-forming mesenchymal neoplasm, predominantly affecting adolescents and young adults. "Jun Ah Lee reported osteosarcoma patients with high RANKL/TNFSF11 expression were less responsive to neoadjuvant chemotherapy, and RANKL overexpression was associated with shorter survival." (PMID 38594779, 2024).
osteoarthritis (52 papers, 2009 to 2026). A noninflammatory degenerative joint disease occurring chiefly in older persons, characterized by degeneration of the articular cartilage, hypertrophy of bone at the margins and changes in the synovial membrane. "In this study, we identified and validated four differentially expressed genes (CXCL8, CXCL2, DUSP5, and TNFSF11) as promising diagnostic biomarkers for osteoarthritis (OA), which collectively mediate immune regulation, inflammatory responses, and bone remodeling in OA pathogenesis." (PMID 40672822, 2025). "Our study found that AT alleviated osteoarthritis by downregulating TNFSF11 expression in chondrocytes." (PMID 35902802, 2022). "Therefore, it is reasonable to see the significant upregulation of TNFSF11 in osteoarthritis." (PMID 37008941, 2023).
atherosclerosis (44 papers, 2010 to 2025). A disease characterized by the build-up of fatty material and calcium deposition in the arterial wall resulting in partial or complete occlusion of the arterial lumen. "Similarly, SELP (selectin-P) deficiency, one of the hepatic key regulators that in our study was found to be upregulated and linked to atherosclerosis signaling via TNFSF11, reduces atherosclerosis in combined P-selectin/ApoE knock-out mice vs. ApoE single knock-out mice." (PMID 35897797, 2022).